RAPSN (receptor associated protein of the synapse)
Description:
Postsynaptic protein required for clustering of nicotinic acetylcholine receptors (nAChRs) at the neuromuscular junction. It may link the receptor to the underlying postsynaptic cytoskeleton, possibly by direct association with actin or spectrin.
Synonyms: RAPsyn; RNF205; CMS1D; CMS1E; CMS11; CMS4C; FADS
Tractability: Antibody: its Gene Ontology location is reachable by antibodies, with high confidence; UniProt places it where antibodies can reach, with medium confidence; the Human Protein Atlas places it where antibodies can reach. PROTAC: UniProt records ubiquitination sites on it.
Gene: Protein-coding gene on chromosome 11 (47,437,762 to 47,449,192, reverse strand). Ensembl gene ENSG00000165917.
Subcellular location: Cell membrane; Postsynaptic cell membrane; Cytoplasm, cytoskeleton
Subcellular location (Human Protein Atlas): Centrosome; Cytosol; Plasma membrane
Gene Ontology:
Molecular function: acetylcholine receptor binding; ionotropic glutamate receptor binding; protein-macromolecule adaptor activity; protein-membrane adaptor activity; structural constituent of postsynaptic specialization
Biological process: synaptic transmission, cholinergic; chemical synaptic transmission; positive regulation of neuromuscular synaptic transmission; establishment of protein localization to postsynaptic membrane; maintenance of postsynaptic specialization structure; neuromuscular junction development; neurotransmitter receptor localization to postsynaptic specialization membrane; regulation of postsynaptic membrane organization; skeletal muscle acetylcholine-gated channel clustering
Cellular component: neuromuscular junction; plasma membrane; cytoskeleton; Golgi apparatus; membrane; postsynaptic membrane; postsynaptic specialization membrane; synapse
Genetic constraint (gnomAD): Loss-of-function variants: 33 observed, 40.42 expected, observed/expected ratio (o/e) 0.82, 90% interval 0.62 to 1.09. The upper end of that interval is the gene's LOEUF score, 1.09, which puts it in group 4 of 6, group 1 being the genes least tolerant of losing a copy. Missense variants: 519 observed, 524.98 expected, observed/expected ratio (o/e) 0.99, 90% interval 0.92 to 1.06. Synonymous variants: 244 observed, 214.83 expected, observed/expected ratio (o/e) 1.14, 90% interval 1.02 to 1.26.
Homologues: Orthologues: chimpanzee RAPSN (99% identical), rabbit RAPSN (97% identical), dog RAPSN (97% identical), rat Rapsn (97% identical), mouse Rapsn (96% identical), guinea pig RAPSN (92% identical), macaque RAPSN (82% identical), tropical clawed frog rapsn (82% identical), zebrafish rapsn (75% identical), Caenorhabditis elegans rpy-1 (33% identical), Drosophila melanogaster CG1909 (30% identical). Paralogues in human: TTC28 (22% identical), GPSM2 (21% identical), GPSM1 (20% identical), TTC24 (11% identical), TTC29 (10% identical), GPSM3 (3% identical).
Diseases named in the same sentence as RAPSN in open-access papers:
RAPSN is named in the same sentence as 38 diseases in open-access papers, as found by Europe PMC text mining. Sharing a sentence is not in itself a finding about the gene and the disease. The quoted sentences say what the papers report.
congenital myasthenic syndrome (12 papers, 2015 to 2026). Congenital myasthenic syndrome (CMS) is a group of genetic disorders of impaired neuromuscular transmission at the motor endplate characterized by fatigable muscle weakness. "Biallelic pathogenic variants in RAPSN cause a form of congenital myasthenic syndrome (CMS), which is typically characterized by fatiguable muscle weakness, hypotonia, and feeding difficulties that present in the neonatal period or early childhood." (PMID 41158980, 2025). "In this report we present the 30-year follow-up of this patient and the diagnostic proceedings which have led to the diagnosis of congenital myasthenic syndrome (CMS) due to pathogenic variants in the RAPSN gene (NM_005055.5)." (PMID 36591657, 2023). "We here present the case of a patient with a congenital myasthenic syndrome (CMS) due to pathogenic variants in the RAPSN gene." (PMID 36591657, 2023). "Another report suggested that intronic mutations in AK9 may act as a disease modifier in combination with RAPSN mutations in limb-girdle congenital myasthenia, but causality or a mechanism of action was not determined." (PMID 38100419, 2023).
glaucoma (3 papers, 2020 to 2023). Increased pressure in the eyeball due to obstruction of the outflow of aqueous humor. "Consistently, RAPSN rs3740685 was nominally associated with glaucoma (subtype unspecified) in UKB (P = 0.0017)." (PMID 32528159, 2020). "Among these loci, 20 were significantly associated with keratoconus, and one (RAPSN rs3740685) was significantly associated with glaucoma after Bonferroni correction." (PMID 32528159, 2020).
lung carcinoma (3 papers, 2021 to 2023). "The decreased methylation of RAPSN would upregulate the function of RAPSN and further accelerate downstream pathways, which was positively correlated with the development of lung cancer." (PMID 36817446, 2023).
arthrogryposis (2 papers, 2023). A rare, non-progressive congenital disorder characterized by multiple joint contractures which are present at birth. "RAPSN mutations are responsible for a CMS where an early onset presentation may include malformations present at birth (arthrogryposis), respiratory distress, hypotonia, and poor feeding." (PMID 37176748, 2023).
breast carcinoma (2 papers, 2016 to 2019). "Previous findings for cg06418238 in RPTOR, cg00736299 in MGRN1, and cg27466532 in RAPSN that were recently reported to be associated with breast cancer risk were not replicated by our study." (PMID 31101124, 2019). "An analysis published after the systematic review reported CpG sites cg06418238 in RPTOR, cg00736299 in MGRN1, and cg27466532 in RAPSN to be more commonly hypomethylated in breast cancer cases, although these associations were not replicated by the Melbourne Collaborative Cohort Study (MCCS)." (PMID 31101124, 2019).
Escobar Syndrome (2 papers, 2022 to 2023). "While CHRNG mutations caused Escobar syndrome for 75 patients of known cases, a number of patients had a genetic etiology associated with variants in the TPM2, CHRND, CHRNA1, MUSK, MYH3, RAPSN, and DOK7 genes." (PMID 36292632, 2022).
cerebral small vessel disease (1 paper, 2025). Cerebral small vessel disease is the term currently used to pathological processes that affect the brain parenchymal circulation (arterioles, capillaries, and veins). "Further, consistent with findings that AD and VaD often co-exist, our AD TWAS identified genes that were associated with lacunar and ischemic strokes, as well as cerebral small vessel disease in other studies, including SLC39A13, RAPSN, MAF1, and MME." (PMID 40141087, 2025).
Diplopia (1 paper, 2023). Diplopia is a condition in which a single object is perceived as two images, it is also known as double vision. "In a review of 10 patients with RAPSN mutations, it was suggested that diplopia without clear ophthalmoparesis could serve as a reliable criterion for differentiating rapsyn-CMS mutations from CMS caused by mutations affecting the number of AChR expressed in the NMJ." (PMID 37176748, 2023).
distal arthrogryposis (1 paper, 2018). A muscle tissue disease characterized by congenital joint contractures of hand and feet. "Expression of several genes linked to motor neuronopathy and familiar amyotrophic lateral sclerosis (EPHA4, IGHMBP2, VAPB, BICD2, and DYNC1H1) or distal arthrogryposis (MYH8, ZC4H2, MUSK, RAPSN) were significantly upregulated or downregulated." (PMID 29727687, 2018).
Hydrocephalus (1 paper, 2021). Hydrocephalus is an active distension of the ventricular system of the brain resulting from inadequate passage of CSF from its point of production within the cerebral ventricles to its point of absorption into the systemic circulation. "Four genes were found to be involved in four cases each: the RAPSN gene related to fetal akinesia syndrome II, the SLC26A3 gene related to congenital chloride diarrhea, the L1CAM gene related to hydrocephalus with X-linked inherence, and the FOXC2 gene related to lymphedema-distichiasis syndrome." (PMID 34682862, 2021).
hyperkyphosis (1 paper, 2019). "Hyperlordosis or hyperkyphosis were reported in patients carrying SCN4A, RAPSN, or SYB1 mutations." (PMID 30808424, 2019).
keratoconus (1 paper, 2020). A degenerative, structural disorder of the eye, characterized by a cone-shaped protrusion of the cornea. "We found that 20.6% (20/97) of the CCT-loci were significantly associated with keratoconus but only the RAPSN locus was associated with POAG after correction for multiple testing." (PMID 32528159, 2020).
multiple pterygium syndrome (1 paper, 2010). "Recent work has tied several human FADS and multiple pterygium syndrome cases to mutations in nicotinic acetylcholine receptors as well as mutations in RAPSN a protein that is associated with acetylcholine receptors." (PMID 20333300, 2010).
cancer (3 papers, 2020 to 2026). A tumor composed of atypical neoplastic, often pleomorphic cells that invade other tissues. "Transcriptome sequencing analysis and qRT-PCR showed that NA elevated the mRNA expression of ARG2, MMP1, S100A4, and RAPSN in granulocytes, thereby reducing the anti-cancer function of granulocytes." (PMID 36817446, 2023). "The immunosuppressive mechanism of NA can be described as follows: NA elevated the mRNA expression of ARG2, MMP1, S100A4, and RAPSN in granulocytes, thereby inhibiting the CKA of granulocytes and promoting cancer development." (PMID 36817446, 2023). "In contrast, ginsenoside Rg1 downregulated the mRNA expression of ARG2, MMP1, S100A4, and RAPSN, and upregulated the mRNA expression of LAMC2, DSC2, KRT6A, and FOSB, thereby enhancing the anti-cancer function of granulocytes inhibited by NA." (PMID 36817446, 2023).
autosomal recessive disease (1 paper, 2022). Autosomal recessive form of disease. "Our data suggests a higher risk for some autosomal recessive diseases in Acadians, notably those associated with AIRE, BCHE, ETFDH, RAPSN and SLC17A5 (2 variants)." (PMID 35488281, 2022).
myopathy (1 paper, 2019). A disease of the muscle in which the muscle fibers do not function properly. "Our first diagnostic hypothesis was either myopathy or collagen VI pathology, but molecular analysis of the COL6A1, COL6A2, COLA613, RAPSN genes did not reveal any rare or pathogenic variant." (PMID 31614862, 2019).
RAPSN also shares sentences with these, for which no sentence is quoted: tumor (3 papers); leukemia (2); memory impairment (2); Atrophy (1); channelopathies (1); congenital myopathies (1); hydrops (1); Hyperglycemia (1); Hyperlordosis (1); Impaired glucose tolerance (1); ischemic stroke (1); Lambert-Eaton myasthenic syndrome (1); lymphedema-distichiasis syndrome (1); myasthenia (1); myasthenia gravis (1); ophthalmoplegia (1); prostate carcinoma (1); ptosis (1); Respiratory insufficiency (1); rhabdomyosarcoma (1); Type 2 Diabetes (1); Vocal cord paralysis (1).